ANXA2 (annexin A2)
Diseases named in the same sentence as ANXA2 in open-access papers (continued):
Sharing a sentence is not in itself a finding about the gene and the disease.
tumor (continued). "HO-1 induction in tumor cells prevented both, the ANXA2 intracellular relocation and the decrease in Ca2+ concentration." (PMID 32197509, 2020). "Recently report claimed that 20(S) G-Rh2 directly bound Annexin A2 and promoting apoptosis in tumor cells." (PMID 33292331, 2020). "The results of the present study showed that AnxA2 is significantly overexpressed in tumor tissues of TNBC patients compared with ER and/or PR, HER2 patients and normal breast tissues." (PMID 33374917, 2020). "The use of immunohistochemistry to detect the presence of CAR T cells, vasculature, and ANXA2+ cells in the tumour would clarify the function of CAR(2448) in vivo." (PMID 31936170, 2020). "On the other hand, the presence of factors secreted by tumor cells impacted not only on Anxa2 levels in bone cells, diminishing its gene expression, but also induced a shift of ANXA2 subcellular localization." (PMID 32197509, 2020). "It has been shown as novel players in predicting tumor recurrence and promotes tumorigenesis by inhibiting ANXA2 phosphorylation in HCC." (PMID 33102579, 2020). "Other studies demonstrated that T-2 phosphorylates Annexin A2 (ANXA2) and activates NF-κB protein, further promoting tumor cell invasion and metastasis." (PMID 33117801, 2020). "Bioinformatics analyses indicated that ANXA2, which is known as a tumor‐promoting gene, served as the potential target of miR‐613.13, 14 Western blot assays were used to detect the expression of ANXA2 after the transfection of miR‐613 mimic in NPC cells." (PMID 31859457, 2020). "In young-PD patients ERG/MYC/NEDD4L/MAOA oncogene panel was found to be activated whereas in old-PD patients HLA-A/B/ANXA2/LDHB/ID4 tumor suppressor panel was down regulated." (PMID 33575208, 2020). "Accordingly, a significant reduction in ANXA2 expression was detected in the tumor samples compared with normal adjacent tissue (p < 0.001)." (PMID 32197509, 2020). "Mice bearing ANXA2-overexpressing GBM exhibited shorter survival times compared with control tumor-bearing mice, whereas OSMR knockdown increased the survival time and diminished ANXA2-mediated tumor invasion, angiogenesis, and growth." (PMID 32248843, 2020). "Studies using Matrigel plug assays and xenograft models have indicated the potential of targeting Annexin A2 in angiogenesis and tumor growth in vivo." (PMID 32629869, 2020). "AnxA2 is produced by a wide spectrum of cell types, including endothelial, trophoblast, epithelial, and tumor cells, as well as innate immune cells, such as macrophages, monocytes, and dendritic cells." (PMID 32575495, 2020). "We found that exo-AnxA2 expression was higher in the sera of AA TNBC patients in comparison to CA TNBC patients (P < 0.0001) even after adjusting the tumor grades in AA and CA TNBC patients." (PMID 31992335, 2020). "Here we investigated the role of ANXA2 in the regulation of H2O2-dependent signaling that drives tumor progression." (PMID 30959964, 2019). "The addition of anti-PD-1 therapy to Lm-ANXA2 resulted in a similar increase in expression of the anti-tumor cytokines of interest within infiltrating immune cells as compared to Lm-ANXA2, with a significant increase in IFNβ." (PMID 31113479, 2019). "Ki-67 and PCNA immunohistochemistry showed that miR-204/211, miR-148a/152 and sh-ANXA2 attenuated the tumor cell growth induced by LncCCAT1." (PMID 31695775, 2019). "Through bioinformatical analysis and experimental analyses, here we confirmed that miR155HG is overexpressed in GBM and acts as a ceRNA for the tumor suppressor miR-185 to upregulate ANXA2." (PMID 30898167, 2019). "In vivo limiting dilution assay revealed that LncCCAT1 overexpression in MCF-7 cells significantly increased tumor incidence, while miR-204/211, miR-148a/152, or sh-ANXA2 lentivirus abrogated the LncCCAT1-enhanced tumorigenicity of MCF-7 cells in vivo." (PMID 31695775, 2019).
tumor (continued). "In vivo imaging of the nude mice at 1, 11 and 21 d after implantation revealed that tumor growth was significantly inhibited at 21 d in the group with decreased ANXA2 expression." (PMID 30898167, 2019). "This study describes the development of the first human ANXA2-targeted, vaccine-type immunotherapy and its anti-tumor effects in the setting of combination immunotherapy for PDAC." (PMID 31113479, 2019). "This study examined the expression of HE4 and ANXA2 in malignant tumor cells originated from different tissues." (PMID 31210752, 2019). "In tumor cells, the expression is mainly membranous, similar to that observed for ANXA2 and the expression of ANXA9 is mainly associated with the degree of differentiation of the tumor, with higher expression in well differentiated cases." (PMID 30744186, 2019). "A priming effect of Lm-ANXA2 treatment was anticipated as supported by the increases in the TME expression of type I interferons known to facilitate CD8+ T cell anti-tumor function." (PMID 31113479, 2019). "It is possible that the priming effect of Lm-ANXA2 on the tumor microenvironment is important for sensitizing PDACs for anti-PD-1 antibody and that it would require multiple doses of Lm-ANXA2 to prime PDACs for the anti-PD-1 antibody treatment." (PMID 31113479, 2019). "Tumor-bearing mice were treated with Cy, either Empty Lm or Lm-ANXA2, in context of either anti-PD-1 antibody or IgG as described in prior study schemes." (PMID 31113479, 2019). "This in vivo study showed that silencing of SNHG14 increased the miR‐613 expression level, which subsequently down‐regulated ANXA2 expression and suppressed tumour growth." (PMID 31513352, 2019). "IHC of tumor sections from the sh-ANXA2 and control groups confirmed decreased ANXA2 levels lead to inhibition of tumor growth in vivo." (PMID 30898167, 2019). "The high expression of ANXA2 activated tumor cells to generate cytoskeleton, acted a positive role in proliferation of GC cells." (PMID 31186633, 2019). "On the other hand, the high expression of ANXA2 activated the pathway for tumor cells to grow filopodia, it provided energy for cancerous cells to move themselves." (PMID 31186633, 2019). "In this study, we detected the ANXA2-specific T cell response within the tumor microenvironment in the liver metastases of a transplant tumor model." (PMID 31113479, 2019). "ES-2 cells which had both high expression of HE4 and ANXA2 were much stronger in proliferation, adhesion, invasion, and migration than other tumor cells." (PMID 31210752, 2019). "After CLG-ANXA2 was taken up by tumor cells, shANXA2 prohibited ANXA2 messenger (m)RNA expression and decreased its protein level." (PMID 29598816, 2018). "WGS data of this tumor revealed that g.chr15: 60,656,550 (ANXA2 intron 4) was aberrantly fused to g.chr15: 72,157,966 (MYO9A intron 32), which was confirmed by PCR sequencing analysis of genomic DNA." (PMID 30361512, 2018). "As a multifunctional protein, ANXA2 was reported to have a role in tumor cell adhesion, migration and invasion, proliferation, neovascularization and angiogenesis and membrane trafficking." (PMID 29568351, 2018). "There is little to none ANXA2 staining in the initial stages (I, II and III) of CRC progression and a marked increase in ANXA2 levels in stage IV tumours and metastatic lesions." (PMID 30050103, 2018). "Further, our recent study of the functional role of AnxA2 in establishing a favorable tumor microenvironment for migrating TNBC cells provides additional support for AnxA2 as an independent and reliable prognostic predictor for DMFS." (PMID 29416802, 2018). "Previous studies on ANXA2 have attempted to neutralize its role in cell to cell adhesion and promoting tumor cell invasion and angiogenesis." (PMID 29568351, 2018). "The staining pattern we observed has already been described in subcutaneous tumours, where ANXA2 is only expressed in the proliferating edges of the tumour." (PMID 30050103, 2018).
tumor (continued). "ANXA2 mean immunohistochemistry (IHC) score (intensity x staining percentage) was used to define high- and low-ANXA2 tumours and assess the correlation of ANXA2 expression with tumour’s clinical features." (PMID 30050103, 2018). "Third, forced inhibition of Annexin A2 effectively reduces tumor progression both in vitro and in vivo studies." (PMID 29508276, 2018). "Extensive studies have shown that ANXA2 is abnormally expressed in a variety of malignancies, and it exerts tumor promoter or suppressor functions depending on the cancer type." (PMID 30081903, 2018). "Analysis of ANXA2 levels in 20 tumours and their adjacent areas revealed a mean ANXA2 overexpression in tumours of 2.43 times, in a range from 1,180% upregulation to 89% downregulation." (PMID 30050103, 2018). "For example Annexin A2 (ANXA2), found in CA samples only, has been shown as aberrantly expressed in a wide spectrum of tumours, functionally playing an important role in tumour growth and progression." (PMID 30627566, 2018). "Early studies have described ANXA2 overexpression in an increasing amount of tumour types including CRC." (PMID 30050103, 2018). "Because of this heterogeneity, we selected 39 formalin fixed and paraffin embedded primary tumour samples and 8 secondary tumours (liver metastasis), and their normal adjacent counterparts, to evaluate ANXA2 expression." (PMID 30050103, 2018). "In the annexin family, we found the presence of Lewis y antigen structure on ANXA2, and that Lewis y antigen promotes ANXA2-mediated tumor proliferation, adhesion and metastasis." (PMID 29296226, 2017). "We propose that P37 is recruited to tumor cell membrane by ANXA2 as exogenous transporter to pump out cytotoxic substrates for the survival of host cells as well as of themselves." (PMID 28976984, 2017). "We have previously shown the presence of Lewis y antigen structure on ANXA2 and that Lewis y modification promoted ANXA2-mediated tumor adhesion, metastasis, and other malignancy progression processes." (PMID 29296226, 2017). "Annexin A2 has been shown to play an important role in cancer cell adhesion, proliferation, invasion, and metastasis, thus playing a crucial role in tumor development." (PMID 28886730, 2017). "Then, the expression patterns of ANXA2 and its pseudogenes were validated in diffuse glioma specimens (n=99) and non-tumor tissues (n=12) by quantitative real-time PCR (qRT-PCR)." (PMID 29291003, 2017). "In this study, we examined AnxA2 expression in the tumor microenvironment in a preclinical model of PDA which suggests its role in tumor colonization." (PMID 29290958, 2017). "In particular, many studies suggest that annexin A2-mediated tumor cell invasiveness is attributable to the generation of extracellular plasmin through modulation of S100A10 enzyme activity." (PMID 28652618, 2017). "If mycoplasma really works on the sensitivity to a wide variety of drugs in tumor cells, is the effect also initiated by the interaction of P37 and ANXA2?" (PMID 28976984, 2017). "The inhibition of Annexin A2 by gene silencing or small chemical inhibitors, like Withaferin A, significantly reduced cancer cell growth and tumor metastasis." (PMID 28963461, 2017). "Together, our findings demonstrate an unrecognized functional link between intracellular annexin A2 and tumor cell adhesion, migration and in vivo grafting." (PMID 28652618, 2017). "We have previously shown that AnxA2 expression is localized on the tumor cell surface and that cell surface expression increases as pancreatic lesions progress from precursor lesions (pancreatic intra-epithelial neoplasms) to invasive PDA." (PMID 29290958, 2017). "In our findings, we show that the intracellular pool of annexin A2 also plays an important role as a regulator of tumor cell adhesion, migration, and, potentially, secondary dissemination." (PMID 28652618, 2017). "Further, tumor volume of NB xenografts transduced with Lenti-ANXA2-shRNA was smaller than that of the control (p = 0.041)." (PMID 28814318, 2017).
tumor (continued). "A synthetic cell-penetrating version of this peptide (LGRFYAASG-pen) interacts with intracellular annexin A2 and disrupts F-actin and focal adhesions, thus impacting on tumor cell shape and impairing their attachment to the ECM." (PMID 28652618, 2017). "Together, these data show that LGRFYAASG-pen impairs tumor cell adhesion and migration, likely by inhibiting annexin A2-dependent membrane-cytoskeleton attachment and organization of actin-based structures." (PMID 28652618, 2017). "A phase 2 clinical trial involving GVAX (allogeneic granulocyte-macrophage colony stimulating factor-secreting tumor vaccine) identified Annexin A2 (AnxA2) from the sera of patients with PDA, as a metastasis-associated protein." (PMID 29290958, 2017). "Here we identify and characterize the LGRFYAASG peptide as a targeting moiety that binds to intracellular annexin A2 and interferes with tumor cell adhesion and migration in vitro, resulting in impaired tumor grafting in vivo." (PMID 28652618, 2017). "Meanwhile, ANXA2 had been found to be involved in the multidrug resistance (MDR) of tumor cells to chemotherapeutic agents including cisplatin, 5-fluorouracil, Doxorubicin and Topotecan." (PMID 28976984, 2017). "Accumulating evidence suggested a correlation between the deregulation of Annexin A2 expression and tumor progression in many cancers." (PMID 28886730, 2017). "Multivariate analysis showed that Annexin A2 expression in tumor tissues was an independent prognosticator for OS and RFS." (PMID 27121050, 2016). "On the other hand, annexin A2 expression in SW480 cells derived from the primary tumor site of a CRC patient was higher than expression in SW620 cells that were established from a metastatic site in the same patient." (PMID 27468721, 2016). "ANXA2 protein expression correlates with tumor response to chemotherapy, and ANXA2 expression in stromal cells was an independent prognostic factor for DFS." (PMID 27402115, 2016). "It has been suggested that CD147 and Annexin A2 are involved in regulating tumor cell movement, while the regulatory mechanisms are far from clear." (PMID 26716413, 2016). "IHC revealed that positive staining for Annexin A2 expression was localized in cell membrane and cytoplasm of tumor cells." (PMID 27121050, 2016). "The intensity of Annexin A2 expression in tumor tissue was stronger than that in matched adjacent liver tissue." (PMID 27121050, 2016). "Most cells of various types in normal tissues and all tumor cells were stained with uniform intensity for Annexin A2 and PRL-3." (PMID 27482895, 2016). "Our study provides the first evidence that CD147 promotes tumor cell movement and metastasis via direct interaction with Annexin A2 and DOCK3-β-catenin-WAVE2 signaling axis." (PMID 26716413, 2016). "Annexin A2 involved in several pathological processes, such as tumor cell adhesion, proliferation, apoptosis, tumor neoangiogenesis, invasion and metastasis." (PMID 27121050, 2016). "One of the mechanisms enhancing cancer metastasis is the interaction between ANXA2 and its binding proteins, which play an important role in the tumor microenvironment." (PMID 27402115, 2016). "The increase in staining intensity along with the tumor aggressiveness indicates a possible promoting role of Anxa2 in breast tumorigenesis." (PMID 26307676, 2015). "Overexpression of Anxa2 was observed in many types of tumor tissues and was found to contribute to cancer progression." (PMID 26307676, 2015). "Fluorescence resonance energy transfer (FRET) confirmed that MIEN1 physically interacts with AnxA2 and functional studies revealed that they mutually cooperate to accentuate tumor cell motility." (PMID 26272794, 2015). "The potential effects of ANXA2-knockdown in xenograft tumor-bearing mice and the significance of the clinical pathology were evaluated." (PMID 26196246, 2015).
tumor (continued). "Tumor tissues were confirmed by H&E staining, and to verify that the tumor growth rate was influenced by ANXA2 knockdown, the xenograft tumors were dissected to examine ANXA2 expression by IHC." (PMID 26196246, 2015). "A large number of studies have shown a significant change in the level of ANXA2 expression in tumor tissues." (PMID 26362938, 2015). "This is consistent with the literature showing that Annexin A2 is expressed at low levels in brain and is upregulated in response to stresses such as tumours, inflammation and neurodegeneration." (PMID 26289944, 2015). "Extracellular annexin A2 has been shown to mediate the degradation of the extracellular matrix and to promote angiogenesis and tumor growth." (PMID 25806803, 2015). "The finding that TNF-α can stimulate ANXA2-dependent secretion of IL-6 in tumor cells suggests that ANXA2 can also modulate the tumor microenvironment." (PMID 25611381, 2015). "ANXA2 is a calcium-dependent phospholipid-binding protein, widely existing on the cell surface membranes of tumor cells, endothelial cells, macrophages, and monocytes." (PMID 26362938, 2015). "Annexin A2 is a calcium-dependent phospholipid binding protein present on the extracellular side of the plasma membrane of various tumor cells and endothelial cell types." (PMID 25826056, 2015). "In any case, these studies promote the idea that annexin A2 is an interesting therapeutic target in angiogenesis and tumor progression, although they dramatically complicate the landscape with regard to the identity of the real CTX receptor." (PMID 25826056, 2015). "To investigate the effects of ANXA2 knockdown on tumor growth in vivo, we established xenograft NPC tumors in NOD/SCID mice." (PMID 26196246, 2015). "In the snRNA group, inhibition of ANXA2 was found to arrest the cell cycle in vitro and inhibit tumour growth in vivo, which highlighted further insight into understanding the biological features of HCC with high metastatic potential." (PMID 24348815, 2014). "The expression of CALR, annexin A2, and annexin A3 in the tumor tissues was higher than that in the normal tissues." (PMID 24884814, 2014). "The molecular target for Tumor Paint is less clear and was thought to involve matrix metalloproteinase-2, although recent evidence suggests a role for Annexin A2." (PMID 28729960, 2014). "The tumor size, pathological grade, pT status, pN status, and pleural invasion are positively correlated with ANXA2, most likely through the role of ANXA2 in the regulation of MMP-2 and cathepsin B expression." (PMID 24591759, 2014). "Side-by-side comparisons of CALR, ZAG, annexin A2, annexin A3 and Hp showed the different expression between tumor tissues and normal tissues." (PMID 24884814, 2014). "Our study also established the biomedical linkage of the critical over-expression of CALR, annexin A2 and annexin A3 between the urine and tumor tissues of UTUC patients." (PMID 24884814, 2014). "Accumulating evidence indicates that interactions between ANXA2 and its binding proteins are important for the tumour microenvironment and function together to enhance metastasis." (PMID 24348815, 2014). "ANXA2 intensity in tumours was significantly lower (Z=2.530; P=0.011) in the shRNA group (3/4; +) compared with that of the mock (4/4; ++ and +++) and negative (4/4; +++) groups." (PMID 24348815, 2014). "Tumour weights of the shRNA group showed a significant decrease compared with that of the mock group, with measuring the tumour volume at various times and tissue expression of ANXA2." (PMID 24348815, 2014). "Annexin A2 is up-regulated in various tumor types and plays multiple roles in regulating cellular functions such as angiogenesis, proliferation, cell migration and adhesion." (PMID 24489826, 2014). "The expression of ANXA2 is strong in poorly differentiated tumor tissues and is significantly correlated with disease recurrence and patient survival." (PMID 24591759, 2014).